IGF2BP2 (insulin like growth factor 2 mRNA binding protein 2)
Diseases named in the same sentence as IGF2BP2 in open-access papers (continued):
Sharing a sentence is not in itself a finding about the gene and the disease.
pancreatic cancer (continued). "The up-regulation of IGF2BP2 activates the PI3K/Akt signaling pathway to promote the growth of pancreatic cancer cells." (PMID 33550985, 2021). "Upregulation of ALKBH5 or IGF2BP2 were both significantly associated with poor survival in several studies, highlighting the prognostic value of ALKBH5 and IGF2BP2 in pancreatic cancer." (PMID 34239358, 2021). "We first showed upregulation of IGF2BP2 in tumor specimens as compared to normal tissue by IHC analysis of pancreatic cancer TMA." (PMID 31804607, 2020). "Although we explored the mutation types and possible carcinogenic mechanisms of IGF2BP2 and IGF2BP3 in pancreatic cancer, the mechanisms that promote the progression of pancreatic cancer need further study." (PMID 33246429, 2020). "IGF2BP2 is highly expressed in pancreatic cancer patients with poor prognosis, and inhibition of IGF2BP2 can inhibit cancer cell proliferation." (PMID 33552994, 2020). "In the LinkedOmics dataset, the high expression of IGF2BP1, IGF2BP2, and IGF2BP3 was significantly associated with the poor overall survival of pancreatic cancer patients." (PMID 33246429, 2020). "miR-141 suppresses the proliferation of pancreatic cancer by forming the miR-141/IGF2BP2/P13K/Akt axis." (PMID 32767982, 2020). "To investigate the clinical importance of IGF2BP2 in pancreatic cancer, we first determined IGF2BP2 expression by immunohistochemistry (IHC) staining in the pancreatic cancer tissue microarray (TMA) slide containing 82 pancreatic cancer and 54 normal samples." (PMID 31804607, 2020). "Consistent with the results of our Cox regression model in pancreatic cancer, the overexpression of IGF2BP2 in basal-like breast cancer and oesophageal adenocarcinoma predicts short-term survival for patients." (PMID 33246429, 2020). "IGF2BP2 is considered as a prognostic marker in pancreatic cancer, esophagogastric junction adenocarcinoma and CRC." (PMID 32767982, 2020). "To determine the role of IGF2BP2 in pancreatic cancer, we ectopically expressed IGF2BP2 in BXPC-3 cells and found that IGF2BP2 promoted cell proliferation, as detected by MTT assays or cell survival as determined by colony formation assays." (PMID 31804607, 2020). "In pancreatic cancer, Hu X found that IGF2BP2 recognized and bound to long non-coding RNA DANCR (lncDANCR), which increased the stability of DANCR and promoted the development of PAAD." (PMID 33082301, 2020). "To better characterize IGF2BP2 function in pancreatic cancer cells, we generated IGF2BP2 KO in BXPC-3 cells and selected two KO clones (KO#3 and KO#11) for characterization." (PMID 31804607, 2020). "Further analysis confirmed that only IGF2BP2 and IGF2BP3 were associated with pancreatic cancer progression." (PMID 33246429, 2020). "The growth rates of pancreatic cancer cell lines transfected with IGF2BP2 siRNA and IGF2BP3 siRNA were significantly slower than that of cell lines transfected with the NC siRNA." (PMID 33246429, 2020). "To further demonstrate the role of IGF2BP2 in proliferation of pancreatic cancer cells, we performed a rescue, i.e., re-expression of IGF2BP2 in the KO cells." (PMID 31804607, 2020). "Collectively, these findings demonstrat that IGF2BP2 is highly expressed in pancreatic cancer, is an independent predictor of prognosis and performs well in predicting the outcomes of patients with pancreatic cancer." (PMID 31852504, 2019). "To further study the mechanism of IGF2BP2 upregulation in pancreatic cancer, we first investigated the genomic amplification variation and gene expression level of IGF2BP2 the TCGA PADC dataset." (PMID 31852504, 2019). "The expression of IGF2BP2 and miR-141 was detected in pancreatic cancer, and clinical significances were analyzed by statistical analysis." (PMID 31852504, 2019). "In this study, we found that IGF2BP2 was overexpressed in pancreatic cancer and predicted poor clinical outcomes, and IGF2BP2 promoted oncogenesis by activating the PI3K-Akt signaling pathway." (PMID 31852504, 2019).
pancreatic cancer (continued). "A negative correlation between IGF2BP2 mRNA expression and the expression of miR-141 was observed in pancreatic cancer tissues and more importantly, reexpression of miR-141 rescued the oncogenic role of IGF2BP2." (PMID 31852504, 2019). "Compared with the normal pancreatic cell line HPDE, the mRNA and protein levels of IGF2BP2 were upregulated in all 6 tested pancreatic cancer lines." (PMID 31852504, 2019). "We comprehensively reveal the oncogenic role of IGF2BP2 in pancreatic cancer carcinogenesis and confirm that genomic amplification and the silencing of miR-141 contribute to its activation." (PMID 31852504, 2019). "Then, flow cytometry assays were conducted to investigate the potential mechanism by which IGF2BP2 promotes pancreatic cancer cell proliferation." (PMID 31852504, 2019). "Upregulation of IGF2BP2 predicts shorter overall survival (OS) in pancreatic cancer patients by statistical analysis." (PMID 31852504, 2019). "The results showed that IGF2BP2 maintained independence when predicting the OS of patients with pancreatic cancer (HR = 3.895, 95% CI = 1.895–4.634, P < 0.001)." (PMID 31852504, 2019). "The flow cytometry assays further indicated that IGF2BP2 inhibited cell apoptosis and induced cell cycle progression in pancreatic cancer." (PMID 31852504, 2019). "The clinical correlation and survival prediction analysis revealed that IGF2BP2 is a promising and reliable prognostic marker for pancreatic cancer patients." (PMID 31852504, 2019). "In summary, IGF2BP2 is frequently upregulated in pancreatic cancer and the expression of IGF2BP2 is regulated by genomic alterations and the silencing of miR-141." (PMID 31852504, 2019). "To verify this, we detected the expression levels of IGF2BP2 in pancreatic cancer cell lines by RT-qPCR and western blot." (PMID 31852504, 2019). "Rescue experiments showed that IGF2BP2 is a functional target of miR-141 in pancreatic cancer because miR-141 re-expression partially reversed the tumor-promotive effect of IGF2BP2." (PMID 31852504, 2019). "In this study, we found that IGF2BP2 was upregulated in pancreatic cancer and promoted tumor cell proliferation through the PI3K-Akt pathway." (PMID 31852504, 2019). "Silencing IGF2BP2 enhances radiosensitivity in pancreatic cancer." (PMID 40986143, 2025). "In fact, by regulating PD-L1 expression, IGF2BP2 may contribute to immune evasion, further promoting tumour survival in the immune-suppressive microenvironment of pancreatic cancer." (PMID 40427100, 2025). "We show that the ability of LncRNA-PACERR to drive pancreatic cancer is dependent on IGF2BP2." (PMID 35526050, 2022). "Similarly, as an m6A reader, IGF2BP2 promoted stemness-like characteristics and pathogenesis in pancreatic cancer by stabilizing DANCR mRNA." (PMID 36358799, 2022). "Similarly, IGF2BP2 was upregulated and found to be related to a poor prognosis in pancreatic cancer and esophagogastric junction adenocarcinoma." (PMID 33816266, 2021). "However, in the pancreatic cancer datasets described by Segara, Pei, and Badea, IGF2BP2 was overexpressed in pancreatic carcinoma tissue compared with normal tissue, with fold changes of 3.446, 2.657, and 2.01, respectively." (PMID 33246429, 2020). "Our study supports the clinical significance of IGF2BP2 in pancreatic cancer." (PMID 31804607, 2020). "Cox’s proportional hazards model was applied to analyse related factors that may affect the overall survival of pancreatic cancer patients, in which IGF2BP2 and IGF2BP3 were identified as independent prognostic factors." (PMID 33246429, 2020). "Interrogation of TCGA pancreatic cancer RNA seq dataset revealed upregulation of IGF2BP2." (PMID 31804607, 2020). "Moreover, IGF2BP2 expression was inversely correlated with miR-141 expression in 30 pancreatic cancer tissues as detected by RT-qPCR." (PMID 31852504, 2019).
pancreatic cancer (continued). "Moreover, upregulating IGF2BP2 expression promotes pancreatic cancer cell growth by activating the PI3K/Akt signaling pathway in vitro and in vivo." (PMID 31852504, 2019). "Taken together, these results suggest that miR-141 may represent a novel biomarker for pancreatic cancer and that a combination of IGF2BP2 and miR-141 can improve the prediction of outcomes in patients with pancreatic cancer." (PMID 31852504, 2019). "IGF2BP2 locus was amplified in 15.25% of pancreatic cancer samples." (PMID 31852504, 2019). "Taken together, these results indicate that IGF2BP2 is frequently upregulated in pancreatic cancer." (PMID 31852504, 2019). "Our data suggest that IGF2BP2 may serve as a new therapeutic target for patients with pancreatic cancer." (PMID 31852504, 2019). "Therefore, altered methylation of miR-141 promoter regions decreases miR-141 expression levels and enhances IGF2BP2 expression and enhances tumor progression of pancreatic cancer." (PMID 31852504, 2019). "To determine whether IGF2BP2 promotes pancreatic cancer cell growth via the PI3K-Akt pathway in vivo as observed in vitro, we established a subcutaneous xenograft model with different treatments." (PMID 31852504, 2019). "However, the biological functions and molecular mechanisms of IGF2BP2 in pancreatic cancer remain elusive." (PMID 31852504, 2019). "Our findings highlight that IGF2BP2 may be a promising molecular target for the treatment of pancreatic cancer." (PMID 31852504, 2019). "IGF2BP2 promotes pancreatic cancer growth by activating the PI3K-Akt signaling pathway." (PMID 31852504, 2019). "IGF2BP2 is overexpressed in pancreatic cancer tissues compared with control tissues." (PMID 31852504, 2019). "However, we found that overexpression of IGF2BP2 induced Ser473 phosphorylation of Akt which suggests that IGF2BP2 promotes pancreatic cancer cell survival via activation of the Akt signaling pathway." (PMID 31852504, 2019). "Gene amplification is common in human pancreatic cancer and significantly contributes to the overexpression of IGF2BP2, which suggests that upregulation of IGF2BP2 might induce oncogenic effects in pancreatic cancer." (PMID 31852504, 2019). "However, the function of IGF2BP2 on proliferation of pancreatic cancer cells was analyzed in our research." (PMID 31852504, 2019). "In addition, similar results of IGF2BP2 were found in pancreatic cancer and endometrial cancer." (PMID 38724996, 2024). "It has been reported that IGF2BP2 could represent an independent predictor of pancreatic cancer." (PMID 35526050, 2022). "However, it remains to be determined as to whether IGF2BP2 can regulate expression of long-non-coding RNAs (lncRNAs) through m6A modifications, leading to self-renewal of cancer stem cells (CSCs) in pancreatic cancer." (PMID 31804607, 2020). "Taken together, these results indicate that the promotion of cell proliferation ability by IGF2BP2 is reversed to certain extents by the re-expression of miR-141, which is consistent with our hypothesis that IGF2BP2-mediated PI3K-Akt activation promotes pancreatic cancer growth." (PMID 31852504, 2019). "However, the clinical significance, role and molecular mechanisms of IGF2BP2 in pancreatic cancer remain unclear." (PMID 31852504, 2019). "HMGA2 upregulates IGF2BP2 expression, stabilizes m6A‐modified amyloid beta precursor‐like protein 2 (APLP2) mRNA, and promotes pancreatic cancer." (PMID 40448344, 2025). "IGF2BP2 binds to METTL14 m6A‐modified TGFB2 mRNA and upregulates TGFB2 expression, resulting in enhanced gemcitabine resistance in pancreatic cancer." (PMID 40448344, 2025). "Together, IGF2BP2 and DANCR enhance the cancerous properties of pancreatic cancer, contributing to its pathogenesis." (PMID 40271153, 2025). "As the stabilizers of m6A methylation, IGF2BP2 and IGF2BP3 can enhance the stability of B3GNT6 and spermine synthase (SMS) mRNA and protein expression, respectively, to promote the progression of pancreatic cancer." (PMID 36981005, 2023).
pancreatic cancer (continued). "miR-141 regulates IGF2BP2 in PDAC, and IGF2BP2 activates the PI3K-Akt pathway in vivo and promotes pancreatic cancer growth." (PMID 37151887, 2023). "For instance, in pancreatic cancer, IGF2BP2 acts as an m6A reader to regulate the expression of DANCR, thus promoting the proliferation and invasion of pancreatic cancer cells." (PMID 36871072, 2023). "We proved that LncRNA-PACERR promotes malignant progression of pancreatic cancer through two pathways: as ceRNA sponging miR-671-3p to activate the KLF12/AKT/c-myc pathway and interacting with IGF2BP2 to enhance KLF12 and c-myc stability." (PMID 35526050, 2022). "IGF2BP2, for example, modulated lncRNA DANCR expression in pancreatic cancer to promote cell proliferation by acting as an m6A reader." (PMID 36257938, 2022). "For instance, IGF2BP2 enhances DANCR stability, functioning as an m6A reader for m6A-modified DANCR mRNA in the maintenance of pancreatic cancer stemness." (PMID 36438499, 2022). "In pancreatic cancer, CMTM4, LAMB3, and IGF2BP2 all promote tumor proliferation, invasion, and metastasis through this activation pathway while inhibiting the cell cycle and apoptosis to play a carcinogenic role." (PMID 35783291, 2022). "In pancreatic cancer, it has also been proven the role of miR-141 in IGF2BP2 (IGF2 mRNA-binding protein 2); which is known to play oncogenic roles." (PMID 35095996, 2021). "A recent study identified that IGF2BP2 targets the lncRNA DANCR through m6A modification, and they work together to promote stemness and pathogenesis in pancreatic cancer." (PMID 33816259, 2021). "A recent study found that m6A reader IGF2BP2 regulates lncRNA DANCR to promote cancer stemness-like properties and pancreatic cancer pathogenesis." (PMID 34497315, 2021). "For example, we have recently shown that IGF2BP2 recognizes the m6A modified DANCR and promotes pancreatic cancer pathogenesis." (PMID 34809621, 2021). "An m6Ascore based on the expression of IGF2BP2, IGF2BP3, KIAA1429, METTL3, EIF3H and LRPPRC is proposed as an indicator of TME status and is instrumental in predicting the prognosis of pancreatic cancer patients." (PMID 34332578, 2021). "IGF2BP2 acts as a reader for the m6A modification of DANCR and promotes pancreatic cancer cell proliferation." (PMID 34239358, 2021). "The relationship between IGF2BP2 and PI3K/Akt signaling pathway has been discussed, suggesting up-regulated IGF2BP2 in pancreatic cancer plays a role in cell proliferation." (PMID 32514248, 2020). "IGF2BP2 and IGF2BP3 are key factors in promoting the progression of pancreatic cancer and are closely related to overall survival." (PMID 33246429, 2020). "Here, we provide evidence that DANCR is a novel m6A modified target that can be recognized by IGF2BP2, leading to an increased stability of DANCR in pancreatic cancer." (PMID 31804607, 2020). "As expected, IGF2BP2 and IGF2BP3 proteins were significantly increased in pancreatic cancer cells compared with HPDE6-C7 cells, while the expression of IGF2BP2 and IGF2BP3 in pancreatic cancer cells was further increased." (PMID 33246429, 2020). "As predicted in the GSEA above, we inferred that IGF2BP2 and IGF2BP3 promote the proliferation or metastasis of pancreatic cancer cells to accelerate progression." (PMID 33246429, 2020). "IGF2BP2 can be a reader of m6A-modified lncRNA-DANCR and functions to stabilize DANCR, which in turn jointly promotes cancer stemness-like properties and pancreatic cancer pathogenesis." (PMID 32398132, 2020). "Among the family members, the expression levels of IGF2BP2 and IGF2BP3 were significantly increased in pancreatic cancer tissues." (PMID 33246429, 2020). "Both IGF2BP2 and IGF2BP3 have great potential to become biomarkers for pancreatic cancer, as verified in patients." (PMID 33246429, 2020). "IGF2BP2 and IGF2BP3, which are related to pancreatic cancer progression and survival, were further analysed, and their functions were verified in vitro." (PMID 33246429, 2020).
pancreatic cancer (continued). "Further clinical correlation analysis of IGF2BP2 and IGF2BP3 confirmed that IGF2BP2 and IGF2BP3 are fundamental factors in promoting pancreatic cancer progression." (PMID 33246429, 2020). "Together, these results suggest that DANCR is a novel target for IGF2BP2 through m6A modification, and IGF2BP2 and DANCR work together to promote cancer stemness-like properties and pancreatic cancer pathogenesis." (PMID 31804607, 2020). "However, high IGF2BP2 mRNA upregulation rate with a relative low genomic copy number gain rate suggested that other regulation mechanisms might play important roles in IGF2BP2 overexpression in pancreatic cancer." (PMID 31852504, 2019). "Furthermore, IGF2BP2 activates the m6A–SLC1A5–mTORC1 signaling axis, thereby enhancing glutamine uptake and promoting pancreatic cancer progression." (PMID 40986143, 2025). "The m6A reader IGF2BP2 could interact with the lncRNA DANCR and promote cancer stemness-like properties and pancreatic cancer pathogenesis." (PMID 34497315, 2021). "Interestingly, DANCR is modified at N6-methyladenosine (m6A), whereas IGF2BP2 serves a reader for m6A-modified DANCR and stabilizes DANCR RNA in pancreatic cancer." (PMID 35141227, 2021). "Furthermore, pancreatic cancer patients with lower METTL3, METTL14, RBMX, FTO, ALKBH5, YTHDF1, and YTHDC1 mRNA expression levels or higher VIRMA, HNRNPA2B1, EIF3A, IGF2BP1, IGF2BP2, and IGF2BP3 mRNA expression levels had significantly poorer OS (P < 0.05)." (PMID 34330301, 2021). "A recent study has highlighted that IGF2BP2 may serve as a reader for m6A-modified DANCR and stabilize DANCR RNA in pancreatic cancer." (PMID 35141227, 2021). "For example, IGF2BP2 serves as a reader of m6A-modified lncRNA-DANCR and can stabilize DANCR, which reversely contributes to tumor stemness-like properties and the pathogenesis of pancreatic cancer." (PMID 33816266, 2021). "Furthermore, we performed a prognostic analysis of IGF2BP1, IGF2BP2, and IGF2BP3 in pancreatic cancer with the LinkedOmics and GEPIA datasets." (PMID 33246429, 2020). "Additionally, miR-141 directly targets IGF2BP2 and can reduce PI3K/AKT activity and inhibit pancreatic cancer proliferation." (PMID 32391379, 2020). "IGF2BP2 serves as an m6A reader to modify DANCR and favors the oncogenicity of pancreatic cancer." (PMID 32767982, 2020). "However, the expression levels of IGF2BP2 and IGF2BP3 were higher in pancreatic cancer tissue than in normal pancreatic tissue." (PMID 33246429, 2020). "Quantitative analysis showed that IGF2BP2 was upregulated in pancreatic cancer tissues compared with paired nontumor tissues." (PMID 31852504, 2019). "Data mining from Gene Expression Omnibus (GEO) datasets showed that IGF2BP2 was upregulated in pancreatic cancer tissues (T) compared with nontumor tissues (NT)." (PMID 31852504, 2019). "The KH3-4 domain of the m6A reader proteins IGF2BP2 and IGF2BP3 specifically recognised the m6A-modified YAP1 transcripts, thereby stabilising YAP1 mRNA and increasing YAP1 protein expression, which in turn promoted colony formation and invasion in pancreatic cancer cells." (PMID 42231052, 2026). "Several independent datasets indicated that IGF2BP2 was expressed at high levels in OSCC tissues and that high expression predicts a worse prognosis than low expression, consistent with studies on acute myelocytic leukemia, hepatocellular carcinoma, and pancreatic cancer." (PMID 35299748, 2022). "Therefore, IGF2BP2-DANCR axis may not only serve as a valuable biomarker, but also provide opportunities for therapeutic intervention in pancreatic cancer." (PMID 31804607, 2020). "However, the role of IGF2BP2 in pancreatic cancer has not been established." (PMID 31852504, 2019). "In the GSE62452 dataset, we found a high expression of IGF2BP2 and IGF2BP3 in pancreatic tumor tissues compared with adjacent non-tumor tissue." (PMID 34332578, 2021).